TET1 (tet methylcytosine dioxygenase 1)
Diseases named in the same sentence as TET1 in open-access papers (continued):
Sharing a sentence is not in itself a finding about the gene and the disease.
tumor (continued). "The results showed that TET1 knockdown significantly increased the killing effect of sorafenib on tumor cells, although TET1 knockdown alone also inhibited the proliferation of HCC cells to a certain degree." (PMID 38967794, 2024). "We have demonstrated that NAD+ metabolism drives IFNγ-induced PD-L1 checkpoint expression via TET1 and promotes tumor immune evasion." (PMID 38177099, 2024). "We found the TETl, TET2, and TET3 protein levels in tumor tissues were significantly lower than those in para cancerous tissues, and the decrease of TET1 has a positive correlation with the decrease of 5-hmC in tumor tissues." (PMID 37266610, 2023). "As a DNA demethylator, TET1 has been known to play a broad tumor suppressor role through demethylating and activating tumor suppressor genes." (PMID 37020036, 2023). "Here, we investigated possible oxygen state-dependent non-enzymatic functions of TET1 in cancer, which we found interestingly switch TET1 from being tumor-suppressive in normoxia to oncogenic in hypoxia." (PMID 37020036, 2023). "This was also supported by IHC staining for the phosphorylation of Akt at T308 and Gsk3β at S9 in tumor tissues of Brafm/+; Tet1−/− and Brafm/+; Tet1+/+ mice." (PMID 37020036, 2023). "There is abundant evidence showing that TET1 upregulates the expression of tumor suppressor genes by restoring 5-hmC levels of their promoter regions, thus playing tumor suppressor functions." (PMID 37020036, 2023). "The oxygen state-governed distinct functions of TET1 demonstrate the importance of tumor microenvironment in determining the roles of key molecules in cancer and provide a rationale for situation-based designing of therapeutic strategies." (PMID 37020036, 2023). "TET1 has thus been extensively studied particularly for its function in the epigenetic reprogramming that plays a critical role in oncogenesis and tumor progression." (PMID 37020036, 2023). "TET1, TET3, and 5hmC levels are associated with tumor hypoxia, advanced differentiation grades, poor OS, and DFS in BC patients." (PMID 38203443, 2023). "Previous studies have shown that TET1 is bound to promoter regions of tumor‐suppressive genes and enhances their expression." (PMID 36345848, 2023). "The classical oxidizing enzymatic activity of Ten Eleven Translocation 1 (TET1) and its tumor suppressor role are well known." (PMID 37020036, 2023). "TET1 and 5hmC were downregulated in primary colon cancer compared with wild-type surrounding tissues and inhibited tumor growth by derepressing inhibitors of the WNT pathway." (PMID 36979633, 2023). "Studies confirmed that abnormalities in DNA methylation are crucial in tumor formation, and the dysregulation of TET1 level was found in multiple malignancies such as gastric, lung, breast cancer." (PMID 37430206, 2023). "The data also showed that tumor volume and weight in Brafm/+; Tet1−/− mice were significantly smaller than those of Brafm/+; Tet1+/+ mice." (PMID 37020036, 2023). "First of all, we compared the expression levels of TET proteins between tumor and normal samples and found that only TET1 had an elevated expression level in HCC samples compared with the normal samples in three independent datasets." (PMID 37181808, 2023). "Mutations of ARID2, CUL3, TET1, FBXW7, EZR and GPHN were frequently accompanied by copy number loss consistent with their predicted/documented tumour suppressor roles." (PMID 38106039, 2023). "Growth of the tumor xenografts was blocked not only when TET1 was induced early after the tumor cells’ inoculation (with both cell lines) but also several days afterwards when the tumors were already established." (PMID 35269796, 2022).
tumor (continued). "Inhibition of PRC2 core factor EZH2 by a specific inhibitor was able to restore TET1 expression and suppress TNBC cell propagation, providing us with a novel strategy for TET1 induction and tumor suppression." (PMID 35805009, 2022). "In TET2MT tumor cells, TET1 and TET3 partially compensate for TET2 activity and contribute to the pathogenesis of TET2MT hematopoietic malignancies." (PMID 36203205, 2022). "Further studies are needed to confirm the molecular mechanisms that identify IL-1β-dependent TET-1 overexpression as a prerequisite for tumor progression and bone metastasis." (PMID 36499741, 2022). "Mutations in TET1, a DNA demethylase, were enriched in responders to ICB and were strongly associated with enhanced tumor immunogenicity and a relatively hot immune microenvironment." (PMID 36092890, 2022). "The results of immunohistochemical staining showed that the expression levels of KI67, GPX4, SLC7A11, and TET1 in the tumor tissues of NOD-scd mice injected with Atranorin@SPION were significantly lower than those in the control group." (PMID 36237989, 2022). "The authors demonstrated that the inhibition of oncogenic EGFR leads to binding of TET1 to tumor suppressor promoters and induces their re-expression through active DNA demethylation." (PMID 35269796, 2022). "Low 5hmC levels exist in a variety of solid tumors and cancer cell lines, implying a tumor-suppressive function of DNA hypomethylation and TET1." (PMID 35805009, 2022). "The family of TET genes (TET1, TET2, and TET3) have been implicated as tumour suppressors in haematological malignancies." (PMID 35055013, 2022). "For the TET1 gene, previous studies found that tumor infiltrating lymphocytes, particularly the cytotoxic ones, were more abundant among the TET1-mutated tumors." (PMID 36358851, 2022). "The results revealed that TET1-mutated patients had better OS, higher TMB and neoantigen load, reinforced tumor immunogenicity, activated antitumor immunity, and more mutation number of DDR pathways than those without." (PMID 35395805, 2022). "The tumor repressive activity of TET1 in the B-lymphocyte lineage has been verified in Tet1−/−Tet2−/−mice." (PMID 36203205, 2022). "Distinct TET1 expression levels and localization were seen in normal and tumor tissue, or when comparing tumors from different patients." (PMID 35646706, 2022). "Taken together, TET1 functions mainly as a tumor suppressor and it reactivates downstream signaling pathways in a tissue-specific manner." (PMID 35805009, 2022). "Endogenous Tet1 proteins were able to precipitate Cul4A/B, VprBP and Uhrf1 in the tumor cell line MCF7, which showed higher levels of Tet1s." (PMID 36056023, 2022). "The results demonstrate correlations among SMYD2, EZH2s, and TET1 expression in the tumor tissues of GIST patients, further verifying the results of the previous experiments from a clinical perspective." (PMID 35668081, 2022). "In the same paper, the authors demonstrated that TET1 catalytic domain overexpression reverses the methylation pattern of different tumor suppressor genes and leads to inhibition of cancer cell tumorigenic potential." (PMID 35646706, 2022). "The in vivo experiments showed that knocking down/overexpressing TET1 significantly affected the tumor size, volume and weight." (PMID 36195596, 2022). "Such tumor-promoting and repressive functions of TET1 and TET3 are most likely cancer type-specific." (PMID 36203205, 2022). "Overexpression of TET1 or TET2 can cause a global decrease in 5-mC, and mutation affecting the TET2 enzyme are critical in tumor development and particularly in leukemia." (PMID 35327559, 2022).
tumor (continued). "To confirm the role of Wnt/β-catenin pathway played in tumor suppression mediated by TET1, we downregulated the TET1 and β-catenin at the same time." (PMID 34926132, 2021). "Remarkably, TET1-expressing PCa cells often occurred in big clusters, and these clusters were observable at all tumor stages." (PMID 34844636, 2021). "In most tumours, TET1 reverses the inactivation of hypermethylated antioncogenes and acts as an “activator”." (PMID 34656178, 2021). "It is known from the literature that miR-767 drives tumorigenesis in other cancers via repression of the tumor suppressors TET1 and TET3, which are responsible for the transformation of 5-methylcytosines to 5-hydroxymethylcytosines (5hmC) in DNA." (PMID 34073664, 2021). "We found that positive miR-106b-5p expression was significantly correlated with low levels of TET1 in tumour specimens, with the tumour specimens positive for miR-106b-5p usually presenting low E-cadherin and high Vimentin expression." (PMID 33985545, 2021). "In PCa tissues, TET1 has been found to be downregulated, and in xenograft models, TET1 depletion facilitates tumor growth and PCa metastasis." (PMID 34844636, 2021). "Here, we review the roles of TETs as context-dependent tumor-suppressor genes and/or oncogenes in solid tumors, and we discuss the current understandings of the oncogenic role of TET1 and its therapeutic implications in TNBCs." (PMID 34209564, 2021). "From in vivo findings, it was concluded that chrysin reduced tumor growth and promoted TET1 expression." (PMID 33858433, 2021). "The tumour/normal TL ratio was significantly correlated with the 5-hmC level (high vs. low; P = 0.043) and frequency of low expression levels of TET1, TET2, and TET3 (0 vs. 1-3; P = 0.043)." (PMID 33758594, 2021). "Collectively, the study directed that chrysin displayed anti-tumor properties through regulating TET1 expression." (PMID 33858433, 2021). "While TET2 appears to have a clear role as a tumor suppressor, the function of TET1 in oncogenesis is equivocal as a tumor suppressor vs a driving oncogene." (PMID 36618446, 2021). "In lymphoid lineage malignancy, however, TET1 appears to play a tumor suppressor role comparable to TET2." (PMID 36618446, 2021). "The results showed the lower expression of TET1 in tumor tissues compared with adjacent normal tissues." (PMID 34926132, 2021). "After EGFR inhibition, TET1 binds to the promotor of the tumour suppressor genes and induces its repression through DNA demethylation." (PMID 34656178, 2021). "TET1 converts 5m to 5-hydroxymethylcytosine (5hmC), so downregulation of TET1 results in hypermethylation and repression of several tumor suppressor genes." (PMID 34901003, 2021). "Comparison of PCa patients considering the tumor stages (pT2 to pT4) and Gleason scores (GS ≤ 6 to ≥ 9) revealed that “TET1-high” foci were detectable in PCa at any tumor stage and Gleason grade." (PMID 34844636, 2021). "Overexpression of TET1 inhibits tumour cell invasion and xenograft tumour formation by activating tissue inhibitors of metalloproteinases." (PMID 34656178, 2021). "The inhibition of TET1 leads to abnormal hypermethylation of the tumor suppressor genes, which results in an increase of tumor malignancy and stemness." (PMID 33953349, 2021). "TET1 initiates the process of DNA demethylation, which often plays a role in tumor suppression in cancers, to promote DNA hydroxymethylation in the promoter regions of its target genes." (PMID 34731191, 2021). "In PCa, TET1 was frequently detected in alpha-methylacyl-CoA racemase (AMACR)–positive tumor cell clusters and was detectable at all tumor stages and Gleason scores." (PMID 34844636, 2021).
tumor (continued). "The findings indicated that specific tumor-related miRNAs and the expression of their potential target genes were altered in TET1-depleted BCPAP cells." (PMID 32089682, 2020). "TET1 is an important hydroxymethylase that activates the expression of multiple genes and plays an important role in development and tumor." (PMID 32577122, 2020). "As a frequently downregulated gene, TET1 acts as a tumor suppressor in multiple malignancies such as breast, gastric, colon, nasopharyngeal, and renal cancer." (PMID 32528872, 2020). "Herein, we found TET1 was expressed in normal bladder urothelium and downregulated or even lost in tumor tissues." (PMID 32528872, 2020). "Surprisingly, the expression levels of classic tumor-suppressor genes miR-7 and miR-15/16 significantly decreased after silencing TET1, while let-7e expression was upregulated." (PMID 32089682, 2020). "TET1 is involved in tumor inhibition by promoting cell apoptosis and inhibiting cell proliferation and invasion." (PMID 32206108, 2020). "Compared with that derived from QBC939 cells, the expression levels of TET1 protein were decreased in tumor tissues derived from RG‐QBC939 cells (P = 0.0002)." (PMID 30784212, 2019). "This study provides novel evidence that MYC directly deregulates the expression of TET1 and TET2 in T-ALL to maintain 5mC and 5hmC patterns in a genome-wide fashion, which is associated with tumor cell-specific gene expression." (PMID 31266538, 2019). "We then implanted BX-TET1-OE and BX-TET1-NC cells subcutaneously into nude mice to investigate the role of TET1 in tumor growth suppression in vivo." (PMID 31399111, 2019). "We furthermore validated our findings in mouse T-ALL cells, where TET1 KD using a different shRNA reduced tumor cell proliferation through cell cycle arrest." (PMID 31266538, 2019). "GADD45A binds to R-loops and recruits TET1 (ten-eleven translocation 1) to promote DNA demethylation at the promoter of tumor suppressor TCF21." (PMID 32010626, 2019). "Tumor samples were classified as positive when the mRNA expression levels exceeded 0.580, 0.102, and 1.866 for TET1, TET2, and TET3, respectively." (PMID 31602281, 2019). "Knockdown of TET1 or ectopic expression of TET2 in T-ALL was associated with genome-wide changes in 5mC and 5hmC enrichment and decreased cell proliferation, suggesting a tumor promoting function of TET1, and a tumor suppressing role for TET2." (PMID 31266538, 2019). "Functionally and mechanistically, circTRIM33–12 inhibits HCC proliferation, metastasis and immune evasion by sponging miR-191 and upregulating TET1 expression, indicating its tumor suppressive role in HCC progression." (PMID 31153371, 2019). "Consistently, immunohistochemical analysis of TET1 on xenograft specimens revealed that the expression levels of TET1 protein were decreased in tumor tissues derived from RG‐QBC939 cells compared with that derived from QBC939 cells." (PMID 30784212, 2019). "One of the major targets of TET1 is RASSF5, a tumor suppressor—as TET1 overexpression upregulates RASSF5 expression by inhibiting the hypermethylation of the RASSF5 promoter." (PMID 31426393, 2019). "In accordance with the in vitro results, TET1 overexpression impaired tumor growth in the animal model; volumes and weights of implanted tumors were significantly decreased in the TET1 OE group compared to the NC group (P < 0.01)." (PMID 31399111, 2019). "miR-494 can trigger gene silencing of multiple invasion-suppressor miRNAs by inhibiting genomic DNA demethylation via the direct targeting of TET1, thereby leading to tumor vascular invasion." (PMID 31656200, 2019). "Collectively, we conclude that TET1 exerts its anti-tumor functions in NPC cells by suppressing Wnt/β-catenin signaling via demethylation of Wnt antagonists (DACT2 and SFRP2)." (PMID 30075814, 2018).
tumor (continued). "Taken together, these results strongly suggest a cell growth regulatory role of TET1 in neuroendocrine cells of the small intestine and function as candidate tumor suppressor gene." (PMID 30045709, 2018). "From the 38th day after a single transfection on, the size of the subcutaneous tumor from the nude mice treated with TET1-CD was remarkably smaller than that from the nude mice treated with TET1-mCD and empty vector." (PMID 30551127, 2018). "As TET1 was downregulated in NPC and expressed in normal septum deviation, the tumor repressive of TET1 overexpression on the growth of NPC cells was evaluated." (PMID 30075814, 2018). "In a wide variety of human cancers, reduced expression of TET1 and TET2 proteins and loss of 5hmC has been documented, and the tumor suppressive role of TET proteins is extensively associated with the prevention of tumorigenesis." (PMID 30045709, 2018). "To evaluate the role of TET1 in tumor growth in vivo, we subcutaneously transplanted equal numbers of control ES-2 cells or ES-2 cells stably expressing TET1 into the left and right flanks of nude mice, respectively." (PMID 29156803, 2017). "Afterwards, we determined 5hmC levels in tumor tissue samples and demonstrated that they were dramatically increased in TET1-overexpressing tumors." (PMID 29156803, 2017). "To demonstrate that the observed decrease in the tumor cell proliferation rate was due to the TET1-dependent activation of RASSF5, we performed RASSF5 knockdown experiments." (PMID 29156803, 2017). "Histological analysis demonstrated that the levels of 5hmC, TET1 and TET3 were significantly associated with tumor hypoxia, tumor aggressiveness and poor prognosis." (PMID 26869355, 2016). "Consistent with our in vitro results, TET1 knockdown was correlated with accelerated tumor growth and increased formation of metastatic peritoneal nodules." (PMID 27121319, 2016). "TET1 also exhibits tumor suppressor function through regulation of the Wnt signaling pathway in colon cancer cells." (PMID 27977763, 2016). "Nevertheless, both methylation and expression of a subset of important tumor-related genes were significantly altered in TET1-depleted CRC cells." (PMID 27977763, 2016). "It indicated the crucial role of TET1 as tumor suppressor in B-NHL as well as a novel potential target for its treatment." (PMID 27183914, 2016). "It is well established that an aberrant hypermethylation of tumor DNA can be caused by mutations in epigenetic modifiers such as IDH1, IDH2, TET1, TET2, and SDH-subunits." (PMID 26848979, 2016). "Ectopic expression of TET1 catalytic domain suppressed colony formation and induced apoptosis of tumor cells of multiple tissue types, supporting its role as a broad bona fide tumor suppressor." (PMID 27225590, 2016). "In conclusion, we found a novel mechanism that TET1 suppresses tumor cell growth, migration and invasion through demethylation of CpG island in PTEN promoter by increasing 5-hmC content." (PMID 27121319, 2016). "Another recent study showed that TET1 acts as a tumor suppressor by regulating the Wnt signaling pathway in CRC." (PMID 27977763, 2016). "We discovered frequent promoter methylation of TET1 in a large set of tumor cell lines and primary tumors, and confirmed its tumor suppressive functions and demethylation activity in tumor cells." (PMID 27225590, 2016). "Collectively, TET1 as a tumor suppressor increases PTEN expression and inhibits AKT and FAK, thus limiting the induction of metastasis." (PMID 27121319, 2016).